PDLIM2 (PDZ and LIM domain 2)
Diseases named in the same sentence as PDLIM2 in open-access papers (continued):
Sharing a sentence is not in itself a finding about the gene and the disease.
tumor (continued). "Of note, in the first two days after injection, both empty vector and PDLIM2-expression plasmids were also detected at high levels in those tissues but quickly cleared afterward (data not shown), consistent with the well-documented tumor-specific enrichment of nanoparticles." (PMID 39718207, 2024). "Furthermore, whether PDLIM2 is involved in therapeutic resistance and whether PDLIM2 exerts its tumor suppressor role through targeting RelA and/or STAT3 have not been examined in any cancer type." (PMID 31757943, 2019). "On the other hand, PDLIM2 nanotherapy induces MHC-I expression and lymphocyte tumor infiltration but does not up-regulate PD-L1." (PMID 39718207, 2024). "Further analyses demonstrated that of the tumours with high macrophage infiltration (CD68 moderate/high scoring stroma), 70% of these were CD68+/CD206+, compared with PDLIM2- negative stroma where 54% of macrophages expressed CD68 and CD206." (PMID 36531051, 2022). "This demonstrated that in the stroma of PDLIM2-positive and PDLIM2-negative tumours the percentages of CD4+, CD8+ or Foxp3+ T cells present in all tissues and stroma were similar, regardless of PDLIM2 expression." (PMID 36531051, 2022).
cancer (24 papers, 2015 to 2025). A tumor composed of atypical neoplastic, often pleomorphic cells that invade other tissues. "Of note, the therapeutic efficacy of epigenetic therapy depends on PDLIM2 expression, and PDLIM2 heterozygous loss causes spontaneous lung and other cancers." (PMID 39718207, 2024). "PDLIM2 represses multidrug resistance genes and cancer-associated genes, rendering cancer cells susceptible to immune attack and treatment." (PMID 37894409, 2023). "Importantly, constitutive activation of NF-κB is implicated in the development of many cancers, and PDLIM2 expression has also been shown to be downregulated during this process, which raises the question: what is the connection between the two?" (PMID 40476213, 2025). "PDLIM2 expression was associated with the TMB in 12 cancer types and MSI in five cancer types." (PMID 35121770, 2022). "In addition, PDLIM2 dysregulation is also closely related to several human cancers (e.g., hepatocellular carcinoma), and is associated with poor prognosis of patients, making it a potentially effective target for other cancer types as well." (PMID 40476213, 2025). "One main function of PDLIM2 is to promote the ubiquitination and proteasomal degradation of nuclear activated NF-κB RelA, a physiologically indispensable transcription factor whose persistent activation has been linked to almost all cancer types and inflammation-associated diseases." (PMID 39080804, 2024). "Therefore, high PDLIM2 expression may be an independent risk factor for poor prognosis in these four types of cancers." (PMID 35121770, 2022). "The reason behind the differential expression of PDLIM2 in different caner types, the role that PDLIM2 plays in the pathogenesis of these cancers, and the mechanisms and pathways that are involved are all questions that require further investigation." (PMID 40476213, 2025). "To assess the role of PDLIM2 in cancer growth, we screened a human TissueScan cancer survey panel for the expression of PDLIM2 mRNA in various types of cancers." (PMID 38880883, 2024). "This is in sharp contrast to the Food and Drug Administration (FDA)-approved epigenetic drugs, which can restore PDLIM2 expression in cancer cells with PDLIM2 epigenetic repression." (PMID 39718207, 2024). "Our results indicate that PDLIM2 is more highly expressed in the normal paracancerous tissues of many cancers, compared with cancer tissues." (PMID 35121770, 2022). "The results revealed that the PDLIM2 expression level was positively correlated with the expression of most immune cell markers in these three cancers, particularly in BLCA and KIRP." (PMID 35121770, 2022). "We utilized The Cancer Genome Atlas and Genotype-Tissue Expression database to characterize alterations in PDLIM2 in pan-cancer." (PMID 35121770, 2022). "As previous studies reported that PDLIM mRNA expression levels are regulated by DNA methylation in many cancer types, and we further investigated the DNA methylation on PDLIM2 mRNA expression and survival in PRAD patients." (PMID 35707002, 2022). "On the other hand, PDLIM2 is overexpressed in a variety of cancer types, including PRAD, in which it promotes cell proliferation, malignant transformation, and EMT, supporting its prooncogenic roles." (PMID 35707002, 2022). "We analyzed the relationship between the expression of common immune checkpoint genes and PDLIM2 in 33 cancer types." (PMID 35121770, 2022). "To determine the differences in PDLIM2 expression in human cancers, we examined the RNA-sequencing data of multiple malignancies in The Cancer Genome Atlas (TCGA)." (PMID 35121770, 2022). "We comprehensively characterized PDLIM2 across 33 cancer types and highlight the potential clinical utility of immunity therapy for PDLIM2 expression." (PMID 35121770, 2022). "To further examine the prognostic potential of PDLIM2 in different cancers, we calculated the disease-free interval (DFI) for 33 types of cancer." (PMID 35121770, 2022).
cancer (continued). "PDLIM2, as a cytoskeleton component, can reverse the growth of cancer cells by regulating promoter methylation." (PMID 35121770, 2022). "In this study, we comprehensively evaluated PDLIM2 expression and its correlation with prognosis and metastasis in patients with cancer." (PMID 35121770, 2022). "PDLIM2 can act as a prognostic-related therapeutic target and is correlated with immune infiltrates in pan-cancer." (PMID 35121770, 2022). "The observations with macrophage migration and adhesion are in agreement with previous observations in THP-1 derived macrophages, and the requirement for PDLIM2 in regulating polarized cell migration in epithelial cells and cancer cells in vitro and in vivo." (PMID 36531051, 2022). "PDLIM2 expression was higher in the highest-grade tumors than in low-grade tumors, suggesting that PDLIM2 is involved in promoting cancer progression or metastasis." (PMID 35121770, 2022). "Upon hematoxylin-eosin staining of extracted lungs, we found that PDLIM2-knockout mice had a smaller size and fewer cancer sites than the control mice." (PMID 34203785, 2021). "In many cancers, PDLIM2 levels are epigenetically suppressed by promoter hypermethylation, which blocks transcription." (PMID 34203785, 2021). "The experimental metastasis model with tail vein injection and orthotopic metastasis model injected into kidney all showed reduced lung metastasis cancer formation in PDLIM2 knockout mice comparing control Balb/c mice." (PMID 34203785, 2021). "Different from its epigenetic repression in lung and many other cancer cells, PDLIM2 expression in AMs and monocytes is downregulated by ROS-activated BACH1." (PMID 33539325, 2021). "We believe that these knowledge and new combination therapies are applicable to many other cancer types, particularly given that PDLIM2 repression and RelA and STAT3 activation are common in human cancers." (PMID 31757943, 2019). "To further establish a correlation between DNA methyltransferase and PDLIM2 expression, we determined the effect of 5-aza-dC, a highly specific DNA methyltransferase inhibitor, upon cancer cell PDLIM2 expression." (PMID 26593252, 2016). "Another recent study has shown that expression of tumor suppressor gene, PDZ and LIM domain protein-2, (PDLIM2) is repressed in KSHV-transformed human umbilical vascular endothelial cells (HUVEC) cells and KSHV-associated cancer cells." (PMID 27447661, 2016). "In addition, PDLIM2 plays different roles in the occurrence and development of different types of cancer, and further research on PDLIM2 is conducive to a better understanding of these diseases." (PMID 40476213, 2025). "PDLIM2 production is also repressed in numerous other types of cancer, so it is possible that nanoPDLIM2 may have broader uses in cancer treatment." (PMID 39718207, 2024). "PDLIM2 has been shown to regulate the stability and activity of different transcription factors, and plays a role in various biological processes, including inflammation, immunity, and cancer." (PMID 38880883, 2024). "PDLIM2, located on chromosome 8p21, is frequently disrupted in various cancers." (PMID 37894409, 2023). "The function of PDLIM2 has also been reported in other cancer types." (PMID 37894409, 2023). "PDLIM2 is expressed in epithelial cells, may be repressed in cancer, and is highly expressed in cancer cells that exhibit an EMT phenotype." (PMID 35707002, 2022). "In summary, PDLIM2 can affect pan-cancer prognosis and participate in immune regulation." (PMID 35121770, 2022). "PDLIM2 is a potential target for combination therapy for cancer." (PMID 35121770, 2022). "Although PDLIM2 can inhibit some tumors, it is also highly expressed in invasive cancer cells." (PMID 35121770, 2022). "Notably, PDLIM2 expression significantly affected the prognosis of four types of cancers, including ACC (P = 0.004), BLCA (P = 0.01), COAD (P = 0.008), and KIRP (P = 0.006)." (PMID 35121770, 2022). "PDLIM2 significantly affected the prognosis of various cancers." (PMID 35121770, 2022).
cancer (continued). "PDLIM2 is repressed in most tumors, but is clearly more highly expressed in a few cancer types." (PMID 35121770, 2022). "We evaluated the relationship between PDLIM2 expression and the clinical stage of 33 cancer types." (PMID 35121770, 2022). "This feedback regulation may not be detectable in BMDM monolayer cell cultures, which is consistent with findings in cancer cell lines, even when cell migratory capacity was inhibited by PDLIM2 suppression." (PMID 36531051, 2022). "Additionally, gene expression was related to clinical stage in seven tumors, suggesting that PDLIM2 is involved in promoting cancer progression or metastasis." (PMID 35121770, 2022). "PDLIM2 has an essential regulatory role that may alter the response of cancer cells, and current evidence shows that PDLIM2 is a viable target for cancer therapy." (PMID 34203785, 2021). "PDLIM2 plays an essential role in cancer formation and inhibition." (PMID 34203785, 2021). "Overall, our findings indicate that PDLIM2 is required for cancer formation and metastasis in metastatic kidney cancer, indicating that PDLIM2 may be a new therapeutic target for metastatic kidney cancer." (PMID 34203785, 2021). "After formaldehyde fixation, liver, spleen, and lung tissues from control and PDLIM2 knockout mice were stained with hematoxylin and eosin (H&E), and we found that the size and the number of the cancers in PDLIM2-knockout mice was smaller than that in the control mice." (PMID 34203785, 2021). "PDLIM2 ectopic expression also overcame the acquired resistance to carboplatin and paclitaxel, another chemotherapeutic drug that is often used together with carboplatin as the first-line treatment for lung and many other cancers." (PMID 31757943, 2019). "Mechanistically, through repressing NF-κB/RelA and STAT3, PDLIM2 increases expression of genes involved in antigen presentation and T-cell activation while repressing multidrug resistance genes and cancer-related genes, thereby rendering cancer cells vulnerable to immune attacks and therapies." (PMID 31757943, 2019). "PDLIM2 is expressed in epithelial cells, may be repressed in cancer, and is also highly expressed in cancer cells that exhibit an EMT phenotype." (PMID 26191041, 2015). "Importantly, dysregulation of PDLIM2 can have severe consequences, including cancer." (PMID 40476213, 2025). "Therefore, HIF-1α inhibitors may be a potential strategy for treating cancers resulting from PDLIM2 downregulation." (PMID 38880883, 2024). "The PDLIM2, a protein playing a crucial role in controlling the stability of transcription factors such as NF-kB and STATs in both epithelial and hemopoietic cells, has been found to be abundant in cancer cell lines displaying an epithelial-to-mesenchymal phenotype." (PMID 38473804, 2024). "Although it dramatically increases TILs as well, chemotherapy also induced the expression of PD-L1 on cancer cells, which presumably protects cancer cells from immune attack and thereby restricts further efficacy improvement of its combination with PDLIM2 nanotherapy." (PMID 39718207, 2024). "We investigated whether PDLIM2 expression was correlated with prognosis in patients with cancer." (PMID 35121770, 2022). "In addition, PDLIM2 was also highly expressed in invasive cancer cells." (PMID 35121770, 2022). "Databases and human cancer tissue samples were analyzed to investigate the roles of PDLIM2 and HIF-1α in cancer growth." (PMID 38880883, 2024). "We discovered that circPTPN12 serves as a scaffold, facilitating the interaction between PDLIM2 and OTUD6B, promoting PDLIM2 deubiquitination, maintaining its expression, and exerting its anti-cancer function." (PMID 38992675, 2024). "PDLIM2 has been demonstrated to regulate different signaling pathways, including NF-κB, STAT3, NOS2, TGF-β/Smad, and β-catenin in cancer cells." (PMID 38880883, 2024).
cancer (continued). "After manual curation for biological functions involved in cancer development, both HIC1 (family SPS.14) and PDLIM2 (family SPS.7) were selected as final candidate genes and further validated by Sanger sequencing." (PMID 33672345, 2021). "Restoring PDLIM2 expression can also suppress p65 and STAT3 activity enhance the expression of genes involved in antigen presentation and T cell activation, and inhibit cancer-related genes, thereby rendering cancer cells more susceptible to immune attack." (PMID 40476213, 2025). "PDLIM2 is a putative tumor-suppressor protein that is inhibited by epigenetics in different cancers and is highly expressed in most adjacent noncancerous tissues." (PMID 35121770, 2022). "Similarly, diverse functions in cancers have been observed in many LIM-domain proteins, like LMO-only proteins and PDLIM2, which could be ascribed to the diverse interacting partners." (PMID 38228802, 2024). "However, most studies focused on a single cancer type, and a comprehensive overview of PDLIM2 and its clinical relevance and immune infiltration in pan-cancer is lacking." (PMID 35121770, 2022). "However, the clinical relevance and immune infiltration of PDLIM2 in cancer are not well-understood." (PMID 35121770, 2022).
infection (4 papers, 2011 to 2025). The state of being infected such as from the introduction of a foreign agent such as serum, vaccine, antigenic substance or organism. "Using the LPS mouse model, they have further shown that repression of PDLIM2 in myeloid cells, especially in lung macrophages, is a causal mechanism underlying infection-induced ALI/ARDS and death." (PMID 41346604, 2025). "Following the promising results, we analyzed scRNA-seq data to examine PDLIM2 expression in peripheral neutrophils, as neutrophils are the most abundant leukocytes in human blood and serve as the first line of defense against infection." (PMID 41000764, 2025). "We also examined PDLIM2 protein levels after infection with HCV and found that PDLIM2 increased in the nucleus during infection, consistent with its location and action during NF-KB and HTLV Tax degradation." (PMID 31374104, 2019). "In time course experiments we found that PDLIM2 mRNA levels were 13 fold higher in Huh7.5 cells 4 days after infection, when viral titers peaked, than in uninfected cells." (PMID 31374104, 2019). "Previous studies with mouse tissue haveindicated that isoform 2 of PDlim2 is transcribed in the spleen, lymphocyte andmost highly in the lung, which is considered to be the site of infection forinfluenza virus." (PMID 21625420, 2011). "The increase in PDLIM2 levels in response to a variety of infections implied that PDLIM2 may be an interferon response gene." (PMID 31374104, 2019). "Infection by HCV and flaviviruses strongly induces transcription of the ubiquitin E3 ligase PDLIM2." (PMID 31374104, 2019). "Since we have shown that infection of Huh7.5 cells by ZIKV or DENV increased expression of PDLIM2 and both viruses are known to degrade STAT2, we examined whether PDLIM2 K/O cells were more resistant to ZIKV or DENV infections." (PMID 31374104, 2019). "Since STAT1, STAT2 and likely PDLIM2 protein levels vary among cell types and during infection, we cannot rule out that PDLIM2 does not direct interferon independent degradation of STAT1 in other situations." (PMID 31374104, 2019).
infectious disease (2 papers, 2025). A disorder directly resulting from the presence and activity of a microbial, viral, or parasitic agent in humans. "Our study highlights both the importance and the clinical applicability of PDLIM2 expression as a biomarker to predict the development and progression of infectious diseases after lung infections by viruses like IV and SARS-CoV-2." (PMID 41000764, 2025). "Moreover, while the overall effect of PDLIM2 repression and cell activation in infectious diseases is pathological, they may simultaneously contribute to antiviral activity." (PMID 41000764, 2025). "The studies above provide the first evidence linking PDLIM2 to ALI/ARDS, COPD, ILD/IPF, and lung infection and infectious disease." (PMID 41346604, 2025). "Thus, therapeutic strategies for targeting PDLIM2 should be further explored for the prevention and treatment of COPD, ILD/ILD, ALI/ARDS, and infectious disease." (PMID 41346604, 2025).
adenocarcinoma (1 paper, 2022). A common cancer characterized by the presence of malignant glandular cells. "Analysis of the correlation between PDLIM2 expression and MSI revealed a correlation mainly in adenocarcinoma." (PMID 35121770, 2022).
inflammation (1 paper, 2022). Aberrant reaction of the microcirculation characterized by movement of fluid and leukocytes from the blood into extravascular tissues. "Another ALP family member, PDLIM2, could mediate granulomatous inflammation by suppressing the growth of TH17 cells." (PMID 35647201, 2022).
kidney diseases (1 paper, 2024). "Among them, Daam2, Pdlim2, Asap1, and Sphk2 all of which have a known relationship to kidney diseases." (PMID 39278930, 2024).
PDLIM2 also shares sentences with these, for which no sentence is quoted: leukemia (2 papers); acute respiratory distress syndrome (1); adenoid cystic carcinoma (1); adenoma (1); anaplastic large cell lymphoma (1); asthma (1); breast invasive carcinoma (1); cervical squamous cell carcinoma (1); Chronic colitis (1); chronic obstructive pulmonary disease (1); Crohn disease (1); digestive system tumors (1); glioblastoma multiforme (1); glioma (1); head and neck squamous cell carcinoma (1); infections of the central nervous system (1); interstitial lung disease (1); intestinal gastric adenocarcinoma (1); kidney chromophobe (1); laryngeal squamous cell carcinoma (1); lung adenocarcinoma (1); lung squamous cell carcinoma (1); lymphoid neoplasm (1); metastatic cancer (1); muscular dystrophy (1); pancreatic adenocarcinoma (1); paraganglioma (1); pheochromocytoma (1); prostate adenocarcinoma (1); prostate tumors (1).
A further 9 diseases each share a sentence with PDLIM2 in 1 paper.